DNAJB12 (DnaJ heat shock protein family (Hsp40) member B12)
Description:
Acts as a co-chaperone with HSPA8/Hsc70; required to promote protein folding and trafficking, prevent aggregation of client proteins, and promote unfolded proteins to endoplasmic reticulum-associated degradation (ERAD) pathway. Acts by determining HSPA8/Hsc70's ATPase and polypeptide-binding activities. Can also act independently of HSPA8/Hsc70: together with DNAJB14, acts as a chaperone that promotes maturation of potassium channels KCND2 and KCNH2 by stabilizing nascent channel subunits and assembling them into tetramers. While stabilization of nascent channel proteins is dependent on HSPA8/Hsc70, the process of oligomerization of channel subunits is independent of HSPA8/Hsc70. When overexpressed, forms membranous structures together with DNAJB14 and HSPA8/Hsc70 within the nucleus; the role of these structures, named DJANGOs, is still unclear. (Microbial infection) In case of infection by polyomavirus, involved in the virus endoplasmic reticulum membrane penetration and infection.
Synonyms: DJ10; FLJ20027
Tractability: Antibody: UniProt predicts a signal peptide or a membrane-spanning region. PROTAC: ubiquitination databases record sites on it; its protein half-life has been measured.
Gene: Protein-coding gene on chromosome 10 (72,332,830 to 72,355,167, reverse strand). Ensembl gene ENSG00000148719.
Subcellular location: Endoplasmic reticulum membrane; Nucleus membrane
Subcellular location (Human Protein Atlas): Endoplasmic reticulum; Nuclear membrane
Gene Ontology:
Molecular function: Hsp70 protein binding
Biological process: cellular response to misfolded protein; ERAD pathway; protein folding; protein-containing complex assembly
Cellular component: endoplasmic reticulum; endoplasmic reticulum membrane; membrane; nuclear membrane
Genetic constraint (gnomAD): Loss-of-function variants: 14 observed, 42.99 expected, observed/expected ratio (o/e) 0.33, 90% interval 0.21 to 0.51. The upper end of that interval is the gene's LOEUF score, 0.51, which puts it in group 2 of 6, group 1 being the genes least tolerant of losing a copy. Missense variants: 444 observed, 529.98 expected, observed/expected ratio (o/e) 0.84, 90% interval 0.77 to 0.91. Synonymous variants: 181 observed, 210.66 expected, observed/expected ratio (o/e) 0.86, 90% interval 0.76 to 0.97.
Homologues: Orthologues: chimpanzee DNAJB12 (99% identical), macaque DNAJB12 (99% identical), dog DNAJB12 (95% identical), guinea pig DNAJB12 (95% identical), rat Dnajb12 (94% identical), pig DNAJB12 (94% identical), mouse Dnajb12 (93% identical), rabbit DNAJB12 (91% identical), tropical clawed frog dnajb12 (77% identical), zebrafish dnajb12a (66% identical), zebrafish dnajb12b (65% identical), Caenorhabditis elegans dnj-1 (41% identical), and 6 more. Paralogues in human: DNAJB14 (53% identical), DNAJB1 (22% identical), DNAJB4 (22% identical), DNAJB11 (21% identical), DNAJB5 (21% identical), DNAJB6 (20% identical), DNAJB2 (19% identical), DNAJB13 (19% identical), DNAJB8 (18% identical), DNAJB7 (17% identical), DNAJB9 (15% identical).
Diseases named in the same sentence as DNAJB12 in open-access papers:
DNAJB12 is named in the same sentence as 8 diseases in open-access papers, as found by Europe PMC text mining. Sharing a sentence is not in itself a finding about the gene and the disease. The quoted sentences say what the papers report.
gastric cancer (4 papers, 2021 to 2022). A primary or metastatic malignant neoplasm involving the stomach. "As a result, high DNAJB12 promoted the tumor growth and metastasis of gastric cancer by increasing PCNA and Vimentin but decreasing E-cadherin expression." (PMID 36499297, 2022). "The comparable regulatory network has also reported that miR-152-3p can negatively regulate DNAJB12, while lncRNA HCG18 can promote DNAJB12 by competitively binding to miR-152-3p, which enhances gastric cancer cells proliferation, migration, and invasion." (PMID 36499297, 2022). "The expression of DNAJB12 was upregulated in gastric cancer cell lines than in normal gastric cells by suppressing miR-152-3p-mediated DNAJB12 mRNA degradation." (PMID 36499297, 2022). "An analogous regulatory network has also been reported for DNAJB12, an ER-related J-protein, where the direct targeting of anti-apoptotic DNAJB12 by miR-152-3p is negatively modulated by the lncRNA HCG18 in gastric cancer models." (PMID 34234816, 2021). "Furthermore, a recent study demonstrated that HCG18 acts as a ceRNA for miR-152–3p, thereby derepressing its target gene DNAJB12 to promote the development of gastric cancer." (PMID 34983361, 2022). "HCG18 can increase the expression levels of WIPF1 and DNAJB12 and activate the PI3K/AKT axis in gastric cancer cells, thus promoting gastric cancer progression." (PMID 34976998, 2021).
AIDS (1 paper, 2015). A syndrome resulting from the acquired deficiency of cellular immunity caused by the human immunodeficiency virus (HIV). "Notably, ENTPD4 belongs to the same family as CD39, whose expression has already been associated with AIDS progression; while DNAJB12 is part of the HSP90 pathway, which is involved in the control of HIV latency." (PMID 26367535, 2015). "This is consistent with our observation that a lower expression of DNAJB12, which is part of the HSP90 pathway, correlates with slow or non-progression towards AIDS." (PMID 26367535, 2015).
colorectal cancer (1 paper, 2025). A primary or metastatic malignant neoplasm that affects the colon or rectum. "Finally, we found that in tumors isolated from colorectal cancer patients, PDIA4 and DNAJB12 are highly expressed compared to their healthy tissues; this expression is associated with the induction of the UPR." (PMID 41120732, 2025).
muscular dystrophy (1 paper, 2022). Muscular dystrophy (MD) refers to a group of more than 30 genetic diseases characterized by progressive weakness and degeneration of the skeletal muscles that control movement. "The DNAJB12 protein is a member of the heat shock protein family, with some evidence supporting positive effects of their induction for muscular dystrophy and other muscle wasting conditions." (PMID 36352383, 2022). "Among these candidate genes were DNAJB12, HDAC5, and TRIM8, each belonging to a protein family that is being studied in the context of neurological disorders or muscular dystrophies." (PMID 36352383, 2022).
tumor (4 papers, 2010 to 2025). "Tumor size, surgery type, ALP level, and 4 SE-associated genes (excluding CEP55 and DNAJB12) were significant prognostic factors for LMFS (all, P < 0.05)." (PMID 38254188, 2024). "The expression levels of DNAJB1, DNAJB5, DNAJB6, DNAJB11, DNAJB12, DNAJB13, and DNAJB14 were significantly upregulated in the tumor tissues." (PMID 32984053, 2020). "The up-regulated genes following treatment included heat shock family proteins such as HSP90AA1, HSPA8, DNAJB12, HSPA1L, DNAJA1, HSPA4L, consistently with other array studies in different tumor cell types." (PMID 20920318, 2010). "In the tumor tissues, the protein levels of PDIA4 and DNAJB12 were also higher than normal tissues." (PMID 41120732, 2025).
cancer (2 papers, 2025). A tumor composed of atypical neoplastic, often pleomorphic cells that invade other tissues. "Together, these findings establish that DNAJB12, DNAJB14, and SGTA are required for PDIA4 reflux to the cytosol, where it binds caspase-3 and promotes cancer cell resistance." (PMID 41120732, 2025). "Our data show a novel non-genetic mechanism to inhibit apoptosis and suggest PDIA4, DNAJB12/14, and SGTA as novel therapeutic targets to rescue apoptosis and inhibit proliferation in cancer cells." (PMID 41120732, 2025). "Thus, targeting the DNAJB12/14-HSC70/SGTA axis is a promising strategy to inhibit ERCYS and impair cancer cell fitness." (PMID 40202782, 2025).
infection (1 paper, 2015). The state of being infected such as from the introduction of a foreign agent such as serum, vaccine, antigenic substance or organism. "The identification of DNAJB12 as a potentially important gene is reminiscent of the observation that the HSP40/DNAJ family proteins play a role in infection of various viruses." (PMID 26367535, 2015).
DNAJB12 also shares sentences with these, for which no sentence is quoted: neurological disorders (1 paper).